MICA (MHC class I polypeptide-related sequence A)
Diseases named in the same sentence as MICA in open-access papers (continued):
Sharing a sentence is not in itself a finding about the gene and the disease.
astrocytoma (1 paper, 2011). "Constitutive levels of NKG2D ligands are low in most cells, thus, to examine the effect of U21 upon the surface expression of the NK ligands, we generated U373 astrocytoma cell lines individually stably expressing ULBP1, ULBP2, ULBP3, MICA, or MICB, using retrovirus-mediated gene transfer." (PMID 22102813, 2011).
Atrophy (1 paper, 2013). Any weakening or degeneration, especially through lack of use. "In addition, the total number of MICA/B+CD7+ cells in mild enteropathy was 4.2 times higher than in severe enteropathy, and among IELs, the number of CD7+ cells was twice higher in atrophy than that observed in mild enteropathy or control samples." (PMID 24058482, 2013).
autoimmune thyroid disease (1 paper, 2012). Inflammatory disease of the thyroid gland due to autoimmune responses leading to lymphocytic infiltration of the gland. "We aimed to assess the association of MICA polymorphism with autoimmune thyroid disease (AITD) in Korean children." (PMID 23209462, 2012).
benign breast disease (1 paper, 2018). "Here, we investigate and quantify NK cell marker CD56 and activating ligand MICA in breast tissue with benign breast disease." (PMID 29090365, 2018). "Serial tissue sections from 88 subjects, 44 with benign breast disease (BBD) who remained cancer-free, and 44 with BBD who later developed cancer, were stained with H&E, anti-MICA, and anti-CD56." (PMID 29090365, 2018).
breast invasive carcinoma (1 paper, 2023). "Notably, MICA expression is downregulated in breast invasive carcinoma (BRCA), lung adenocarcinoma (LUAD), lung squamous cell carcinoma (LUSC), pheochromocytoma and paraganglioma (PCPG), prostate adenocarcinoma (PRAD), thyroid carcinoma (THCA) and uterine corpus endometrial carcinoma (UCEC)." (PMID 37784183, 2023).
Chagas disease (1 paper, 2021). A parasitic infection caused by Trypanosoma cruzi. "This study also showed that the MICA*008~HLA-C*06 haplotype was a risk factor for digestive form of Chagas disease." (PMID 34489964, 2021). "Our data showed that the MICA and KIR polymorphisms may exert a role in the LVSD of cardiac patients, and in digestive form of Chagas disease." (PMID 34489964, 2021). "Furthermore, the possible association of these gene polymorphisms with LVSD, the powerful independent predictor of all-cause mortality in patients with CCHD, was also evaluated because MICA alleles and certain KIR genes and their HLA ligands may be related to the clinical forms of Chagas disease." (PMID 34489964, 2021).
cholestasis (1 paper, 2020). Impairment of the bile flow caused by obstruction within the liver, or outside the liver in the bile duct system. "MICA is proteolytically shed from the cell surface of tumor cells by ADAM proteases, and shed sMICA has been detected in sera of many cancer patients, but also in sera of individuals with acute bacterial infections or cholestasis." (PMID 32582150, 2020).
chronic hepatitis B (1 paper, 2014). "Because an increase in soluble MICA levels in the serum of chronic hepatitis B patients is significantly associated with increased susceptibility to HCC, this increase during HBV replication needs to be prevented." (PMID 25026299, 2014).
chronic lung allograft dysfunction (1 paper, 2022). Chronic lung allograft dysfunction encompasses a range of pathologies that cause a transplanted lung to not achieve or maintain normal function. "Antibodies against MICA have been associated with chronic lung allograft dysfunction (CLAD)." (PMID 36346670, 2022).
corneal disorder (1 paper, 2018). A non-neoplastic or neoplastic disorder that affects the cornea. "Attention should be paid to MICA expression levels to avoid potential damage to HCECs in corneal transplantations, corneal keratitis, and other corneal disorders." (PMID 30013574, 2018).
Dysmenorrhea (1 paper, 2015). Pain during menstruation that interferes with daily activities. "High peritoneal fluid levels of MICA were positively correlated with dysmenorrhea, total rAFS score and adhesions rAFS score, though these clinical associations had a moderate correlation coefficient." (PMID 25775242, 2015). "MICA ratio levels also correlated with dysmenorrhea (r=0.232; p=0.029), total rAFS score (r=0.221; p=0.031) and adhesions rAFS score (r=0.221; p=0.031)." (PMID 25775242, 2015). "In addition, MICA presented a clinical correlation with dysmenorrhea (r = 0.232; P = 0.029)." (PMID 25775242, 2015).
endometrial tumor (1 paper, 2021). "We analyzed the surface expression of MICA, MICB, CD112, CD155, and B7-H6 on target endometrial tumor cell lines including Ishikawa, KLE and RL95-2 by flow cytometry." (PMID 34691070, 2021).
enteropathy (1 paper, 2013). "In moderate enteropathy, enterocytes showed large MICA/B+ aggregates oriented to the apical pole and also associated to the perinuclear region." (PMID 24058482, 2013). "Among CD7+lamina propria cells, MICA/B+ cells represented the 2.6% in controls, the 1.9% in severe enteropathy and the 7.6% in mild enteropathy." (PMID 24058482, 2013). "Particularly, some of these CD20+ cells expressed MICA/B+ as shown in severe enteropathy (Figure 4Aiv)." (PMID 24058482, 2013). "Most of the samples with enteropathy showed a discontinuous pattern of MICA/B expression along the epithelium." (PMID 24058482, 2013). "This higher number of lamina propria plasma cells expressing MICA/B is likely due to the massive increment in cellularity, characteristic of severe enteropathy observed in untreated CD patients." (PMID 24058482, 2013). "Remarkably, MICA/B+ T cells were found among intraepithelial lymphocytes (IELs) and in lamina propria, and the number of these cells was increased in severe enteropathy." (PMID 24058482, 2013). "The highest percentage (15.6%) of MICA+CD7+ cells per unit of m.m. was observed in biopsies from patients with mild enteropathy and the total number of MICA+CD7+ cells was 2.3 times higher than in control samples." (PMID 24058482, 2013). "The pattern of MICA/B staining in mucosal tissue in severe enteropathy was similar to that found in in vitro models of cellular stress." (PMID 24058482, 2013). "Particularly, these CD7+MICA/B+ IELs were abundant in biopsies from patients with mild enteropathy." (PMID 24058482, 2013). "We found coarse MICA/B aggregates in the cytoplasma of CD7+ cells; which were more frequently observed in mild enteropathy samples." (PMID 24058482, 2013). "In severe enteropathy, total number of CD7+ cells was significantly increased compared to samples from healthy controls, and a twofold increment in the number of MICA/B+lamina propria lymphocytes in untreated CD patients compared to healthy controls was found." (PMID 24058482, 2013). "In only a few cases of severe enteropathy, macrophages HAM56+ cells (Figure 4Avi) or CD68+ cells (not shown) exhibited MICA/B expression." (PMID 24058482, 2013).
gastric tumors (1 paper, 2021). "According to our data, MICA*002 and MICA*004 alleles could be highly expressed on the surface of gastric tumor cells, which would trigger NKG2D receptor activation and an effective NK cell response." (PMID 33868281, 2021). "We propose that certain MICA alleles have the potential to be more expressed on gastric tumor cells, depending on their cellular microenvironment, which may favor a better or worse immune response mediated by NK cells." (PMID 33868281, 2021). "Gastric tumor cells express MICA protein, a ligand to NKG2D receptor that triggers natural killer (NK) cells effector functions for early tumor elimination." (PMID 33868281, 2021). "Support for this hypothesis comes from reports showing that patients with gastric tumors with high MICA expression had higher overall survival and disease-free-survival than patients bearing tumors with low MICA expression." (PMID 33868281, 2021).
gout (1 paper, 2022). A condition characterized by painful swelling of the joints, which is caused by deposition of urate crystals. "In summary, we provide evidence for the association of CNVR1 containing MICA with gout in Polynesian people, implicating class I MHC-mediated antigen presentation in gout." (PMID 35451026, 2022). "Analysis of European gout genetic association data demonstrated a signal of association at the CNVR1 locus that was an expression quantitative trait locus for MICA." (PMID 35451026, 2022).
head and neck cancer (1 paper, 2024). A primary or metastatic malignant neoplasm affecting the head and neck. "C4A, DDX39B, and MICA/B had associations with risk of head and neck cancers of which one, DDX39B, appeared cancer-subtype-specific and was associated with a lower risk of oropharyngeal cancer [OR: 0.24, 95% CI: 0.13 to 0.43; PP4: 0.94]." (PMID 38684708, 2024).
hemochromatosis (1 paper, 2016). A disorder of iron metabolism characterized by a triad of HEMOSIDEROSIS; LIVER CIRRHOSIS; and DIABETES MELLITUS. "Other related genes include Transporter Antigen Processing (TAP1/2), MHC-class I related chain A/B (MICA/MICB) and hemochromatosis gene (High Fe, HFE)." (PMID 27818635, 2016).
hepatitis B (1 paper, 2018). "The effect of this exchange is more subtle, in that the MICA-129Met variant is associated with increased transcriptional activity but protein retention within intracellular compartments and higher serum MICA levels are seen in patients with hepatitis B who are homozygous for the MICA-129Val allele." (PMID 30166984, 2018).
hyperthyroidism (1 paper, 2020). Overactivity of the thyroid gland resulting in overproduction of thyroid hormone and increased metabolic rate. "Similar to Wang's study, our study provided strong evidence that the MICA‐STR polymorphism might be clinically useful as a pharmacogenetic predictor, and we propose that MICA*A5.1 carriers should be given cautiously treated with ATD for hyperthyroidism and monitored intensely." (PMID 33017098, 2020).
influenza infection (1 paper, 2010). "We predict a cellular stress such as influenza infection would initiate the transport of MICA from their cytoplasmic stores to the basement membrane of epithelial cells." (PMID 20844584, 2010).
invasive carcinoma (1 paper, 2014). A carcinoma that is not confined to the epithelium, and has spread to the surrounding stroma. "By contrast, there was little evidence for heterogeneity by tumor stage for the MICA variants, and a statistically significant association with MICA-A5.1 was observed in invasive carcinoma (OR = 1.46, 95% CI = 1.03–2.07; P = 0.03)." (PMID 24403192, 2014).
ischemia reperfusion injury (1 paper, 2010). Adverse functional, metabolic, or structural changes in ischemic tissues resulting from the restoration of blood flow to the tissue (reperfusion), including swelling; hemorrhage; necrosis; and damage from free radicals. "We previously demonstrated that ischemia/reperfusion injury (IRI) could up-regulate MICA expression on mouse kidney allografts." (PMID 21092233, 2010).
Juvenile onset (1 paper, 2014). Onset of signs or symptoms of disease between the age of 5 and 15 years. "Six of these patients were classified as juvenile-onset SLE and all had anti-MICA (data not shown)." (PMID 24565339, 2014).
Kaposi's sarcoma (1 paper, 2021). A malignant neoplasm characterized by a vascular proliferation which usually contains blunt endothelial cells. "In Kaposi’s sarcoma-associated herpesvirus infection, MICA, which is a ligand for NKG2D activating receptor, undergoes ubiquitination, which prevents its cell surface localization." (PMID 34594338, 2021). "The observation of similar intracellular compartmentalisation and regulation occurring with the NK cell ligand MICA in Kaposi’s sarcoma shows that such a mechanism of regulation may be generalizable across different disease contexts." (PMID 34594338, 2021).
Lyme disease (1 paper, 2013). Lyme disease (named after the towns in the USA where the disease was first identified) is a bacterial infection caused by Borrelia burgdorferi. "MICA is also a ligand for NKG2D on γδ T cells, which have been shown to increase neutralizing antibodies in the absence of CD4 αβ T cells against vesicular stomatitis virus (VSV), foot-and-mouth disease virus, as well as Borrelia burgdorferi, the causative agent for lyme disease." (PMID 23372753, 2013).
lymphocytic leukemia (1 paper, 2021). "Alleles MICA A5.1 (including the most frequent allele MICA*008) frequency was decreased in heterozygous leukemic patients, described only on lymphocytic leukemia, with data for myeloid leukemia, unfortunately, missing." (PMID 33868289, 2021).
Meniere disease (1 paper, 2014). A disease of the inner ear (labyrinth) that is characterized by fluctuating sensorineural hearing loss; tinnitus; episodic vertigo; and aural fullness. "Genes that were revealed to be associated with bilateral Meniere's disease, chronic balance/hearing loss were allelic variants of DRB1, PTPN22, TLR 10, MICA genes." (PMID 25330336, 2014).
metastatic cancer (1 paper, 2016). A carcinoma which has spread from the original site of growth to another anatomic site. "The failure to induce cell-surface MICA expression upon loss of surface adhesion, thereby facilitating immune evasion, could be a significant step in the development of metastatic cancer." (PMID 28154561, 2016).
migraine (1 paper, 2025). "For migraine with aura, MICA (p = 2.82×10−7), GPATCH4 (p = 2.39×10−5), BBS4 (p = 7.64×10−4), ALMS1 (p = 8.40×10−4), and CCDC180 (p = 3.38×10−3) were the five most significant ones." (PMID 41261954, 2025). "Among these genes, the five most significantly associated with migraine were BBS4 (p = 3.60×10−6), PAM (p = 6.50×10−5), MICA (p = 9.60×10−5), BLM (p = 4.35×10−4), and GPATCH4 (p = 7.29×10−4)." (PMID 41261954, 2025).
myelodysplastic syndrome (1 paper, 2025). A clonal hematopoietic disorder characterized by dysplasia and ineffective hematopoiesis in one or more of the hematopoietic cell lines. "The other study was a phase I clinical trial of MICA & MICB KO anti-NKG2D CAR T cells in six patients with relapsed/refractory myelodysplastic syndrome (MDS)/AML." (PMID 41354926, 2025).
myeloid leukemia (1 paper, 2021). A clonal proliferation of myeloid cells and their precursors in the bone marrow, peripheral blood, and spleen. "In this study focused on myeloid leukemias, 3-year cumulative incidence of relapse in patients with MICA mismatched vs MICA matched graft was higher for patients with a matched graft (20% for mismatched versus 35% for matched graft)." (PMID 33868289, 2021).
non-alcoholic fatty liver (1 paper, 2018). A benign form of fatty non-alcoholic fatty liver disease where the disease has not yet progressed to the inflammation of liver. "Patients diagnosed with non-alcoholic fatty liver (NAFL) or non-alcoholic steatohepatitis (NASH) showed significantly increased expression of MICA and MICB on hepatocytes." (PMID 30150983, 2018).
Obesity (1 paper, 2020). Accumulation of substantial excess body fat. "Notably, the number of hepatic NK cells was significantly increased in NASH patients with obesity compared with that in the healthy controls, along with higher expression levels of NKG2D and MICA/B in the liver, suggesting that NK cells may contribute to the progression of NASH through MICA/B." (PMID 32765518, 2020).
parasitic infections (1 paper, 2021). "Cellular stress such as parasitic infections and inflammation can upregulate the expression of MICA." (PMID 33666549, 2021).
penicillin allergy (1 paper, 2020). "We detected an independent intronic lead SNP for the penicillin allergy meta-analysis (GWAS lead variant rs114892859, p value 1.29 × 10−29) in MICA." (PMID 32888428, 2020).
polymyositis (1 paper, 2021). A rare idiopathic inflammatory myopathy characterized by symmetric proximal muscle weakness and elevated muscle enzymes. "Muscle biopsy specimens acquired from polymyositis (PM) patients show an upregulation of MICA/B correlating with IL-15 expression by muscle cells and the identification of CD8+ NKG2D+ cells within inflammatory infiltrates." (PMID 35821998, 2021).
reovirus infection (1 paper, 2023). "To uncover the mechanism by which reovirus infection leads to the reduced expression of MICA, MICB, ULBP2, and ULBP3 in infected cells, we first evaluated their shedding from the cell surface." (PMID 37753084, 2023). "Downregulation of the surface expression of MICA, ULBP2, and ULBP3 was observed in both MNT-1 and U87-MG cells following reovirus infection." (PMID 37753084, 2023). "Thus, we further tested whether the intracellular protein levels of MICA, MICB, ULBP2, and ULBP3 were altered upon reovirus infection." (PMID 37753084, 2023).
spondyloarthritis (1 paper, 2025). "Future studies should thus consider such MICA–HLA-B associations in the context of both genetic risk assessment and functional immunogenetic analysis in spondyloarthritis." (PMID 40806743, 2025). "Several studies have reported associations between specific MICA alleles and susceptibility to spondyloarthritis (SpA), particularly MICA*007, MICA*008, and MICA*009, which have been implicated in increased risk or modulation of disease severity." (PMID 40806743, 2025). "These patterns may reflect underlying linkage disequilibrium structures within the HLA class I region, suggesting that certain extended haplotypes, involving both MICA and HLA-B alleles, could also contribute to genetic susceptibility or modulation of disease phenotype in spondyloarthritis." (PMID 40806743, 2025).
steatosis (1 paper, 2023). Increased lipid within the cytoplasm of cells. "Immunohistochemical staining revealed that the NKG2D ligands MICA/B are upregulated specifically in sections most affected by steatosis compared to healthy sections of the same tissue." (PMID 37774007, 2023).
thrombotic microangiopathy (1 paper, 2021). The syndromes of microangiopathic hemolytic anemia, thrombocytopenia, and variable signs of organ impairment, due to platelet aggregation in the microcirculation. "Graft function was stable until the 5th day and graft biopsy on the 6th day; thrombotic microangiopathy (TMA), C4D negative and inflammatory infiltration of polymorphonuclear leukocytes inside peritubular capillary, and anti-MICA antibodies were positive." (PMID 33976951, 2021).
thyroid cancer (1 paper, 2011). "Our prior study suggests that MAP kinase activation due to BRAF gene mutation in thyroid cancer may contribute to increased MICA/B expression." (PMID 21605422, 2011).
trachoma (1 paper, 2016). "The results showed an association between TLR4 and MICA polymorphisms and trachoma disease severity, as well as with protection." (PMID 27559544, 2016).
Trichiasis (1 paper, 2016). Inversion and rubbing of the eyelashes against the globe of the eye. "The association of TLR4 Asp299Gly and MICA exon 5 microsatellites with inflammatory trachoma (TI) and trichiasis (TI) were examined." (PMID 27559544, 2016).
tuberculosis (1 paper, 2021). A chronic, recurrent infection caused by the bacterium Mycobacterium tuberculosis. "In contrast, MICA*A5 allele was inversely associated with GC; therefore, this variant may be a protective factor for this disease, similar to findings previously reported for other types of cancer and infectious diseases, such as tuberculosis." (PMID 33868281, 2021).
uveitis (1 paper, 2023). An inflammatory process affecting a part of or the entire uvea. "The LINC01149 variation modifies the expression of MICA, making it easier for it to function as a key gene in the susceptibility to uveitis development." (PMID 36980914, 2023).
vasculitis (1 paper, 2021). "Although it is still unclear to what extent NKG2D and its ligand MICA contribute to disease pathogenesis in GCA and GPA, it is interesting that NKG2D and MICA have been implicated in these other forms of vasculitis." (PMID 33815414, 2021).